CD4 (CD4 molecule)
Diseases named in the same sentence as CD4 in open-access papers (continued):
Sharing a sentence is not in itself a finding about the gene and the disease.
tumor (continued). "Tumor-associated macrophages (TAMs) in C6-CD200tr tumors had dendritic cell (DC)-like morphology and CD86 expression, and there were more CD3+, CD4+, and CD8+ cells, and increased expression of granzyme and perforin in C6-CD200tr tumors." (PMID 38540350, 2024). "We observed that the depletion of CD4+ T cells resulted in increased tumor growth in the B6CaP tumor model." (PMID 38701369, 2024). "78% of treated mice survived at least 150 days post tumor implantation, which was primarily mediated by CD4+ T cells." (PMID 38803496, 2024). "Our findings indicate that NSG2 overexpression is associated with increased infiltration of CD4+ and CD8+ T cells near the tumor." (PMID 39493764, 2024). "In contrast, TIM-3 expression was significantly higher in the central than in the peripheral and non-tumor tissues in both CD4+ and CD8+ T cells." (PMID 38335302, 2024). "The induction of CD8+ T cell activity by cDC1 via cross-presentation plays a key role in tumour rejection and immunotherapy and is also critical for the early initiation of CD4+ T cells." (PMID 38475858, 2024). "We have developed an invivo tumour model that utilizes MHCII I-E restriction which limits antigen presentation to tumour-specific CD4 T cells to either tumour-specific B cells or host myeloid antigen presenting cells (APCs) in lymphopenic RAG-/-mice." (PMID 38125720, 2024). "Further, higher TIL density (10% increments) was associated with high levels of tumor markers (CD3, CD4, CD5, CD8) and improved prognosis." (PMID 39507608, 2024). "Similar to the immune cell blocks and tumor signatures that were overrepresented in the poor response group, each of CD4+ Treg, CD4+ TH17, PC7.neg, INT.down, and UNION.down was significantly associated with ICI response in univariate regression analysis." (PMID 39514276, 2024). "In OSCC, PLIN3High tumors harbored obviously less infiltrated CD8+ T lymphocytes and CD4+ T lymphocytes, whereas CD56+ NK cells, CD68+ tumor-associated macrophages (TAMs), and CD19+ B lymphocytes were essentially comparable." (PMID 38554152, 2024). "B7H4 expressed on both tumour and host cells reduces the activation and subsequent effector functions of tumour-infiltrating CD4 and CD8 T cells, such as inflammatory cytokine production and cytolytic activity." (PMID 39061159, 2024). "Regulatory T cells (Tregs), a subgroup of CD4+ T cells that express the FoxP3 gene and have immunosuppressive properties, are found in high numbers in the tumor microenvironment (TME) of different types of malignancies." (PMID 38509593, 2024). "The density of total tumor-infiltrating CD4+ and CD8+ T cells was also increased in the triple-treatment group." (PMID 38564022, 2024). "The signalling induced by these cytokines activates immune cells and drives polarization of CD4 + T cells towards Th1 and Th17 cells with a largely beneficial role in initiating adaptive anti-tumour responses." (PMID 39487861, 2024). "And intratumoral ICOS+PD-1+CD4+Tfh cells preferentially recognize tumor-derived neoantigens compared with other CD4+ subsets." (PMID 38051200, 2024). "CD4+T cells then further activate mononuclear macrophages, inducing inflammatory storms in the tumour and killing the tumour." (PMID 39816386, 2024). "The role of CD4+ T cells in cancer is complex and context‐dependent, as they can exert both tumour‐suppressing and tumour‐promoting effects." (PMID 38973477, 2024). "Analysis of TCR variable regions has uncovered clonal expansion of CD4+ or CD8+ T cells with exhaustion phenotypes due to persistent tumor antigen stimulation." (PMID 38245530, 2024). "The remaining number of tumours split into quite equal parts for “desert” and “excluded” immune phenotypes, except for Foxp3+CD4+ and M1 tumours, where “desert” was more common than the “excluded” immune phenotype." (PMID 39409156, 2024).
tumor (continued). "Based on this information, it can be assumed that the immunosuppressive function of Foxp3+CD4+ T cells in tumour tissue can be driven by PD-L1 expression in these cells localised in tumour islets." (PMID 39409156, 2024). "FKBP12F36V-KRASG12V tumor–bearing mice were randomized to dTAGV-1 treatment or to a combination of dTAGV-1 with either anti-CD8 or anti-CD4 antibodies." (PMID 39718828, 2024). "CD19 + tumor-infiltrating B-cells function as APCs within the TME of MIBC, facilitating the activation of CD4 + tumor-infiltrating T-cells (TIT)." (PMID 38216927, 2024). "The proportion of activated CD4+ T effector cells increased in the tumor region after ipilimumab treatment in one respond patient (P7), and decreased in the tumor region after ipilimumab treatment in one non-respond patient (P8)." (PMID 38448521, 2024). "The whole tumor slide was quantified for CD4, CD8, MHC-II, and DAPI markers and detected the XY location for each cell." (PMID 39149474, 2024). "CDC25B expression in HCC cells had a significant correlation with B cells, CD8+ T cells, CD4+ T cells, macrophages, neutrophils, and dendritic cells in tumor cells." (PMID 39371450, 2024). "Mouse tumor models have proven that TNFRSF9 enhances anti-tumor immune responses by strengthening the functionality of CD4+ T cell, thereby amplifying the effectiveness of CD8+ T cell-mediated responses." (PMID 39232806, 2024). "Within the tumor microenvironment (TME), effector CD4+ T cells and γδ T cells exert a crucial function in immune surveillance against tumor growth." (PMID 38818376, 2024). "The tumor microenvironment consists of various immune cells, such as CD4+ T cells, CD8+ T cells, and Treg cells, which are essential for developing tumor cells within their surrounding environment, separate from the malignant proliferation of cancer cells." (PMID 39518128, 2024). "Next, we investigated the role of CD4+ T cells in both urologic tumor models using CD4-specific depletion or isotype control antibodies." (PMID 38701369, 2024). "Generally, CD4 T cells found in the tumor belonged to the more experienced subsets, while naïve cells were less frequent." (PMID 38742103, 2024). "On the other hand, cDC 2 can activate Th1, Th2, Th17, and CD8 T cells in vitro and drive anti-tumor CD4 T cell immune responses." (PMID 39262952, 2024). "The findings indicated a positive association between the expression of ACSL5 expression and CD8+ T cell (r = 0.405, p = 3.96e‐20), CD4+ T cell (r = 0.493, p = 8.28e‐31), negativity correlated with tumor purity." (PMID 38923758, 2024). "Collectively, These results imply that CD4+ T/CD8+ T/NK cells play an important role in the anti-tumor effect of radiation, but the role of individual cell subpopulations in two irradiation modes is different." (PMID 39736508, 2024). "IHC confirmed the presence of scattered CD4+ T cells in both tumors, mainly located at the tumor periphery." (PMID 39239511, 2024). "Better survival was linked to larger densities of proliferating CD8+ T cells and a higher ratio of CD8+ to CD4+ cells in tumor infiltrates." (PMID 39409094, 2024). "We also found that in vivo daily treatment with LDHi versus vehicle increased the proliferative capacity of CD8+ and CD4+ Teff TILs while reducing tumor cell proliferation, as assessed by Ki67 expression." (PMID 39225102, 2024). "Taken together, these results suggest that the constitutive elimination of CD11chi DCs alters the composition of CD4+Foxp3+ Treg cells in lymphoid tissues under homeostatic and tumor-bearing conditions." (PMID 39206204, 2024). "In the present study, we used a similar model to examine the anti-tumor immune potential of old IEL CD4+ T cells." (PMID 38327516, 2024). "Together, these data suggest that the anti-tumor effect of zebularine depends at least on the co-existence of CD4+ and CD8+ T lymphocytes in the TME." (PMID 38755254, 2024).
tumor (continued). "Since neoantigens are only expressed by cancer cells, they are unique targets for tumor immunotherapy as they stimulate an immune response by activating CD4+ and CD8+ T cells." (PMID 38434964, 2024). "Nevertheless, reducing Treg, although some patients regain the response of CD4+ cells, cannot prevent tumor-mediated immunosuppression, indicating that Treg suppression is not an independent way." (PMID 38240856, 2024). "They found patients in cluster IMM.3 (n = 22) had the longest OS, with tumor samples enriched for PCs, activated memory CD4 T cells, M1 macrophages, and resting NK cells." (PMID 38997411, 2024). "Adaptive anti-tumor immunity, in general terms, relies heavily on cytotoxic responses to tumor neoantigens—a process largely driven by interferon-γ secretion by Th1 CD4 + T cells." (PMID 38689325, 2024). "In vitro studies showed that tumor cells impacted the function of CD4+ Tregs, leading to the secretion of IL-10 and TGF-β1." (PMID 38331927, 2024). "In the tumor cell vaccines, the whole tumor cell is used as the source of the vaccine, which contains whole TAAs, including the CD4+ and Cd8+ T cells’ epitopes." (PMID 38672519, 2024). "Given the specific expression of MHC-II in HPV+ tumor cells and its critical link with CD4+ T cells, we utilized CellPhoneDB algorithm to explore cellular communications through ligand-receptor interactions between tumor cells and CD4 + T cells." (PMID 39105803, 2024). "This discovery aligns with other evidence suggesting that CD4+ T cells are as important as CD8+ cytotoxic T cells for tumour dissemination, and how the activation of CD4+ T cells can influence the fitness of CD8+ T cells." (PMID 38880657, 2024). "ACTB was positively correlated with tumor purity, B cells, CD4+ T cells, CD8+ T cells, neutrophils, macrophages and dendritic cells." (PMID 39896807, 2024). "Identifying the molecules and immune markers responsible for CD4+ T-cell activation is a critical concern in tumor immunotherapy." (PMID 39181686, 2024). "AIRE-mediated alterations in the quality of tumour associated epitopes can also support CD8+ T cell-mediated therapy by generating helper CD4+ T cell epitopes that are also cross reactive against tumour cells." (PMID 39606441, 2024). "Knockdown of Bcl6 in naive CD4+ T cells also resulted in increased differentiation of Th9 cells, which are involved in helminth infections and tumor immunity." (PMID 39456751, 2024). "Its expression levels on CD4+ T cells are a deciding factor for clinicopathological parameters such as tumor size, lymph node involvement, and depth of tumor invasion." (PMID 39275127, 2024). "For TILs and subpopulation detection, TILs were < 10%, and the tumour interstitium was infiltrated by a small number of CD4+ and CD8+ T lymphocytes." (PMID 39624628, 2024). "The number of CD3+/CD4+ cells in the tumor and stroma in pretreated biopsied tissues was markedly lower in pCR tumors than in non‐pCR tumors (p = 0.038 and p = 0.015, respectively)." (PMID 38888366, 2024). "TIM-3 expression on lymphoma-derived ECs sustains tumor onset, growth, and dissemination by inhibiting activation of CD4+ T cells and Th1 polarization, and correlates with poor patient outcome." (PMID 38426109, 2024). "A unique characteristic of cHL is the formation of CD4+ T-cell rosettes, surrounding and protecting the tumor cells, aiding in immune evasion." (PMID 39769007, 2024). "An elevated ratio of CD8+ T cells to CD4+ Tregs in the tumor microenvironment suggests a more effective antitumor immune response." (PMID 38892423, 2024). "Unexpectedly, the depletion of CD4+ T cells only partially reduced the impact on the anti-tumor efficacy of Qβ-HPVag." (PMID 38523774, 2024). "Conversely, the density of CD68+ tumor associated macrophages (TAMs) and PD1−FoxP3+CD4+ regulatory T (TREG) cells was comparable in the mTLSs of HGSOC and NSCLC samples." (PMID 38514660, 2024).
tumor (continued). "In TNBC, Tregs induce an immunosuppressive microenvironment, inhibit CD8+ and CD4+ T-cell activation, and also inhibit the anti-tumor immune response." (PMID 39735530, 2024). "This is particularly evident in the immune cell population surrounding tumor cells, including CD4 T cells, CD8 T cells and CD163 macrophages." (PMID 39025895, 2024). "Together, these results further underscore the importance of polyclonal CD4+ T cells for tumor control corroborating with immune depletion experiments." (PMID 39236156, 2024). "TCR clonality reflects the presence of the highly cloned T cells in the tumor microenvironment, where CD4 + T cells and CD8 + T cells play important roles in the anti-tumor immune responses." (PMID 38280010, 2024). "In fact, blocking the CSF-1/CSF-1R axis results in a decrease in CD4+ Foxp3+ Tregs correlated with a reduction in tumor growth and enhances CD8+ T cell-mediated immunity in the sarcoma TME." (PMID 39457693, 2024). "The immune evasion process also includes reduced expression of the MHC-II, which presents tumor-specific antigens to CD4+ T cells." (PMID 39057061, 2024). "Immunophenotyping of blood and spleen from KPC-Luc tumor-bearing mice showed a decreased number of macrophages and CD4+ T cells, and an increased accumulation of natural killer (NK) cells in comparison to KPC tumor mice." (PMID 38866899, 2024). "The results showed that the proportions of CD4+ T cells, NK cells and Mo-MDSCs in blood weakly correlated with their counterparts in tumor." (PMID 38653982, 2024). "The cytotoxic efficacy of CD8+ T cells depends on the composition of CD4+ T cell subsets within the tumor tissue." (PMID 39543650, 2024). "CD4 + T cells release several proinflammatory cytokines via their subpopulation of T helper (Th) cells to kill tumours; these cells also promote the expansion of CD8 + T cells and increase their function." (PMID 39720956, 2024). "Our findings indicate that both CD8+ and CD4+ naïve T cells are notably enriched in the leading‐edge area of the tumor." (PMID 39716897, 2024). "Conversely, in the murine tumor microenvironment CD4+ T-intrinsic STING activation drives TH1 and TH9 activation." (PMID 39803487, 2024). "Such macrophages in return secrete TGF- β and promote expression of PD1 on CD4+ T cells, resulting in further infiltration of Tregs into the tumor." (PMID 38533720, 2024). "CCL17 (TARC) is highly secreted by Reed–Sternberg cells and is involved in recruiting CD4 + T-cells to the tumor site where they suppress local immune responses by inhibiting the function of cytotoxic CD8+ T-cells." (PMID 39769007, 2024). "One week after a second tumor challenge, T cell infiltration in the brain was assessed, and a significant increase in CD4+ and CD8+ T cell frequency was observed in long-term survivors." (PMID 39399681, 2024). "Consistent with the CNV results, the expression of tumor-associated genes, including KIR3DL2, TOX, TWIST1, and GTSF1, upregulated along the CD4+ T-cell trajectory." (PMID 39963655, 2024). "The infiltration of CD8+ and CD4+ T cells into the tumor, which is crucial for effective tumor immunotherapy, was explored by flow cytometry after different treatments." (PMID 38966855, 2024). "In contrast to uniHELP, neoHELP-induced tumor control was dependent on the presence of CD4+ T cells, while both vaccines relied on CD8+ T cells." (PMID 39040850, 2024). "By preventing the occupation of hematopoietic niches or even helping with tumor colonization of the bone, CD4+ T lymphocytes indeed impact bone metastasis." (PMID 38690280, 2024). "In contrast, the combination of GVAX + anti-PD-1 + anti-CSF-1R increased the infiltration of PD-1+CD137+CD8+, PD-1+CD137+CD4+, and PD-1+OX40+CD4+ T cells within the tumor." (PMID 38434964, 2024).
tumor (continued). "TILs include T cells, B cells and natural killer cells (NK), and in T cells, CD8+ cytotoxic T cells (CTL) are essential for tumour destruction, CD4+ T helper 1 (Th1) cells secrete cytokine mediators that help CTL improve toxicity." (PMID 39624628, 2024). "Correspondingly, the numbers of CD3+ T, CD8+ T, and CD4+ T cells in tumor tissues were the highest in the BG/OVA@EcN‐treated group." (PMID 38009498, 2024). "In contrast, host APC-dependent activation drives a potent CD4+-dependent anti-tumour response in this mouse model." (PMID 38125720, 2024). "Specifically, the virus targets CD4+ T cells, leading to decreased immune competency against infections and neoplasia." (PMID 38542195, 2024). "M2 macrophages reduce tumor-infiltrating lymphocytes (TILs) and induce Tregs, which compromise CD4(+) helper and CD8(+) cytotoxic T (CTLs), NK and antigen-presenting cells." (PMID 38505617, 2024). "In tumor immunity, CD4+ T cells can activate CD8+ T cells through various mechanisms to differentiate into cytotoxic T lymphocytes." (PMID 38887558, 2024). "CAR-T cells armed with IL-7 prolong the persistence of CD4+ T cells and enhance the anti-tumour response." (PMID 38675377, 2024). "In CRC, tumor-infiltrating lymphocytes are composed of anti-tumorigenic CD4+ (Th1 or Th22) and pro-tumorigenic CD4+ (Th17 or Tregs) cells, and the ratio of anti- and pro-tumor T cells is crucial for tumor progression." (PMID 39125923, 2024). "Overall, these correlations are consistent with the results from mouse tumor models which showed reduction in CD4+ T cells upon galectin 7 injection or overexpression." (PMID 38503797, 2024). "Tumor cell infiltration was also identified in 12 of 16 PB samples (0.24–74.0% in PB MNCs), five of which showed expansion of single-chain TCR tumor cells with CD3ε- CD4+ PD1high T-cell populations by FCM, consistent with the LN data." (PMID 38012392, 2024). "Th9 cells are a recently described subpopulation of CD4+ T cells exhibiting controversial effects in cancer immunity, depending on the tumor type." (PMID 38891095, 2024). "We further compared the status of CDMs between the circulating T cells derived from PBMCs and tumor-infiltrating T cells, and results showed that enhancement of cuproptosis is observed in CD4+ T, CD8+ T and Tprolif that derived from PBMCs of patients." (PMID 39575251, 2024). "This involved combining mature DCs with CD4+ T cells and tumor cells obtained from different donors to induce allogeneic T cell activation." (PMID 38745661, 2024). "Further analysis of CD4 + T cells in the tumor revealed that naïve CD4, T helper, and Treg cells were significantly higher in MASH-HCC relative to HCC." (PMID 39402682, 2024). "Compared to the model group, Sor significantly promoted CD4+ T-cell infiltration in the tumor tissues of tumor-bearing mice (P < 0.05), with the PF group and the combination therapy group exhibiting even stronger effects than the Sor group (P < 0.01)." (PMID 38312647, 2024). "Within tumour-infiltrating lymphocytes there was expansion of CD4 and PD-1+ CD8 populations with STAT3 ASO." (PMID 39886125, 2024). "Flow cytometry was used to assess the ratio of CD8+ and CD4+ T cells in the distal tumor and spleen." (PMID 38774946, 2024). "Conventional CD4+Foxp3− T cells (Tconv) is considered as a critical role in the effect of anti-tumor responses." (PMID 39493763, 2024). "This system demonstrated efficient antigen expression and immunostimulation in cultured cells, along with anti-tumour activity in mice accompanied by efficient induction of CD4+ and CD8+ T cells." (PMID 38528828, 2024). "To further explore the role of T cells in the rejection of Mgat5-deficient tumors, we depleted CD4+ and CD8+ T cells separately and found that each depletion led to a partial rescue of Mgat5-KO tumor growth." (PMID 38912584, 2024).